STAT3 (signal transducer and activator of transcription 3)
Diseases named in the same sentence as STAT3 in open-access papers (continued):
Sharing a sentence is not in itself a finding about the gene and the disease.
ovarian carcinoma (continued). "The expression of STAT3/p-STAT3 was upregulated in ovarian cancer samples versus normal ovarian tissue, benign tumours and borderline tumours (OR = 10.14, p < 0.00001; OR = 9.08, P < 0.00001; OR = 4.01, p < 0.00001, respectively)." (PMID 34789292, 2021). "Additional studies are needed to clarify the exact mechanisms and possibilities, as HER2 is an attractive therapeutic target for gastric, colorectal, and ovarian cancer, and the STAT3 signaling pathway is connected with HER2 overexpression in ovarian cancer." (PMID 35054564, 2021). "Suppressing the JAK/STAT3 signal markedly reduces the tumor progression and metastasis of ovarian cancer." (PMID 34330232, 2021). "Epidermal growth factor receptor (EGFR) signalling and the interleukin-6 (IL-6)/signal transducer and activator of transcription 3 (STAT3) are aberrantly activated in ovarian cancer." (PMID 34369236, 2021). "Previous research confirmed that treatment with gefitinib (EGFR inhibitor) led to high STAT3 phosphorylation in ovarian cancer." (PMID 34369236, 2021). "In the current meta-analysis, we assessed the influence of STAT3/p-STAT3 expression on the clinicopathological features and prognosis of ovarian cancer patients, and 16 published articles were included." (PMID 34789292, 2021). "Studies in epithelial ovarian cancer have shown the inactivation of STAT3 can reduce N‐cadherin and vimentin expression and suppress cell migration behavior." (PMID 34231329, 2021). "For instance, hypoxia-induced exosomes enhanced aggressiveness and chemoresistance of ovarian cancer cells through the activation of STAT3." (PMID 34796092, 2021). "Abnormal activation of the JAK/STAT3 signaling pathway, which contributes to the pathogenesis and progression of cancers, was also noted in ovarian cancer." (PMID 34330232, 2021). "STAT3, that is signal transducer and activator of transcription factor 3, relates not only to the proliferation, invasion, metastasis, apoptosis of ovarian cancer cells, but also chemotherapy resistance." (PMID 34820170, 2021). "In ovarian cancer, persistent STAT3 signaling has also been demonstrated to promote tumor survival, invasion, and suppression of antitumor immunity, as well as facilitate resistance to several front-line therapeutics, such as cisplatin and paclitaxel." (PMID 34956861, 2021). "To ascertain the clinical significance of C-MYC, STAT3, and p-STAT3 in ovarian cancer, we assessed their expression in an ovarian tissue microarray (n = 375)." (PMID 34363022, 2021). "Our data finally demonstrated that miR-146b overexpression appears to be more effective in inhibiting ovarian cancer cell migration than inhibition of the STAT3 pathway alone." (PMID 34369236, 2021). "NR1D1 up-regulated the expression of SOCS3, resulting in suppression of the JAK/STAT3 signaling pathway, thus retarding the growth of ovarian cancer cells." (PMID 34330232, 2021). "The CXCL8/STAT3 pathway plays a key role in M2 macrophage polarization and stemness of ovarian cancer stem-like cells." (PMID 35011369, 2021). "High STAT3/p-STAT3 expression was significantly associated with poor OS and unfavourable PFS in ovarian cancer patients." (PMID 34789292, 2021). "A further study demonstrated that genistein can suppress M2 polarization of macrophages and stemness of ovarian cancer through CXCL8/STAT3 signaling." (PMID 35011369, 2021). "Consistent outcomes were found in the ovarian cancer biomarker subgroups (STAT3 and p-STAT3) (STAT3: HR =1.74, 95% CI =1.27–2.39, p = 0.001; p-STAT3: HR = 1.64, 95% CI = 1.36–1.98, p < 0.0001)." (PMID 34789292, 2021). "STAT3/p-STAT3 expression in ovarian carcinoma and borderline ovarian tumour was compared; the data were from 260 ovarian cancer cases and 78 borderline ovarian tumour cases." (PMID 34789292, 2021). "STAT3 is constitutively activated in ovarian cancer and the inhibition of STAT3 pathway effectively suppresses ovarian cancer growth and progression." (PMID 33801098, 2021).
ovarian carcinoma (continued). "Min, Xiao, Gao, and Wu, found that compared with normal ovarian tissue and borderline and benign tumours, the expression level of STAT3/p-STAT3 in ovarian cancer was significantly higher." (PMID 34789292, 2021). "We further found that miR-146b blocked the secretion of IL-6 and markedly inhibited phosphorylation of STAT3 at Tyr705 and Ser727 in ovarian cancer cells." (PMID 34369236, 2021). "High STAT3/p-STAT3 expression was correlated with poorer prognosis of ovarian cancer patients for both overall survival (OS) (HR = 1.67, p < 0.00001) and progression-free survival (PFS) (HR = 1.40, p = 0.007)." (PMID 34789292, 2021). "MTHFD2 functioned as a critical protumorigenic factor involved in ovarian cancer progression via STAT3 signaling pathway." (PMID 34231329, 2021). "Nevertheless, we show that Olaparib, the most widely used PARPi, induced STAT3 activation and expression of several cancer-promoting STAT3 target genes, across several different ovarian cancer cell lines." (PMID 34956861, 2021). "This meta-analysis comprised ovarian cancer and benign ovarian tumour STAT3/p-STAT3 expression data from 7 studies (8 trials)." (PMID 34789292, 2021). "To address this contradiction, we systematically searched for available literature and conducted a meta-analysis to assess the clinicopathological value and prognostic ability of STAT3/p-STAT3 in ovarian carcinoma." (PMID 34789292, 2021). "It was indicated that silencing SOCS3 abolished the function of NR1D1 over-expression on the proliferation and apoptosis of ovarian cancer cells as well as the activation of STAT3 signal." (PMID 34330232, 2021). "We obtained consistent outcomes for the ovarian cancer biomarker subgroups (STAT3 and p-STAT3) (STAT3: OR = 0.22, 95% CI = 0.10–0.47, p < 0.00001; p-STAT3: OR = 0.55, 95% CI = 0.31–0.98, p = 0.042)." (PMID 34789292, 2021). "To confirm and support our findings in ovarian cancer patient tumors, we investigated Olaparib’s effect on STAT3 activation in immune cells and fibroblasts." (PMID 34956861, 2021). "Compared with normal tissues, STAT3 is overexpressed or constitutively activated in about 70% of human solid tumors and in 94% of ovarian cancers." (PMID 33909625, 2021). "For example, STAT3 modulates ovarian cancer cell proliferation by regulating the expression of genes such as cellular myelocytomatosis (c-Myc), cyclin D1, B-cell lymphoma-extra-large (Bcl-xL), and surviving." (PMID 34503128, 2021). "Similar to this finding, a recent study suggests that resveratrol suppresses growth, increases apoptosis as well as autophagic activity in ovarian cancer cells, presumably through blocking STAT3 signaling pathway." (PMID 31949487, 2020). "Persistent activation of STAT3 enhances cell proliferation, survival, invasion, cancer stem cell-like characteristic, angiogenesis and drug-resistance in ovarian cancer." (PMID 31949487, 2020). "Understanding the metabolic characteristics associated with therapy resistance and uncovering the underpinning mechanisms, such as CD44 and STAT3 crosstalk, will provide insight into novel therapeutic interventions to overcome ovarian cancer chemoresistance." (PMID 33335857, 2020). "Recently, an oncolytic adenovirus (M4), which selectively silences STAT3 expression by producing antisense STAT3 complementary DNA, greatly suppresses survival of ovarian cancer cells but sparing normal cells." (PMID 31949487, 2020). "More importantly for the scope of this review, tumor-promoting TAMs have been reported to drive ovarian cancer metastasis, stemness, and therapy resistance with the involvement of STAT3 and CD44." (PMID 33335857, 2020). "Previously, our research team reported that adipose stem cells from visceral and subcutaneous fat facilitated the growth and migration of ovarian cancer cells via IL-6/JAK2/STAT3 pathway." (PMID 32121099, 2020).
ovarian carcinoma (continued). "In this study, we have identified that ID1 confers ovarian cancer chemoresistance largely through the induction of the IL-6/STAT3/ATF6-mediated autophagy." (PMID 32080166, 2020). "The STAT3 signaling is critical for ovarian cancer progression, such as promoting cell proliferation, survival, invasion, stem cell-like characteristic, angiogenesis and chemo-resistance." (PMID 31949487, 2020). "Overexpression of c-Myb in ovarian cancer tissues often leads to a poor prognosis, since c-Myb activates NF-κB and the STAT-3 signaling pathway, which promotes tumor growth, invasion and chemotherapy resistance." (PMID 32934709, 2020). "STAT3 is activated constitutively in many types of tumors, including ovarian cancer, and this activation promotes accelerated cell proliferation, increased regulation of survival factors, and activation of anti-apoptotic proteins." (PMID 33536913, 2020). "Our work revealed that SPTBN1 suppresses the growth and metastasis of epithelial ovarian cancer via SOCS3-mediated blockade of the JAK/STAT3 signaling pathway." (PMID 32516133, 2020). "Curcumin reduces fascin expression through JAK/STAT3 pathway inhibition, which interferes with the cellular interactions essential for the metastasis and recurrence of ovarian cancer cells." (PMID 33213437, 2020). "In ovarian cancer cells, curcumin inhibited the lysophosphatidic acid-induced secretion of IL-6 and IL-8 by inhibiting STAT3 phosphorylation, resulting in reduced cancer cell motility." (PMID 32731620, 2020). "We previously reported that phosphorylation of STAT3 (P-STAT3) occurs in response to chemotherapy treatments in ovarian cancer cell lines." (PMID 33023532, 2020). "CAF-mediated STAT3 activation in ovarian cancer lines also leads to development of cisplatin resistance through the increased expression of antiapoptotic proteins, indicating a prominent role for STAT3 in CAF-induced chemoresistance." (PMID 33335857, 2020). "Here, we will provide an outlook into natural and synthetic inhibitors of STAT3 signaling that have been shown to be effective in ovarian cancer management." (PMID 31949487, 2020). "Relatively high levels of phosphorylated STAT3 are known to correlate with the degree of cisplatin resistance in ovarian cancer models." (PMID 32731620, 2020). "In that context, we have demonstrated persistent activation of STAT3 in advanced-stage ovarian cancer." (PMID 33023532, 2020). "Under the efforts of researchers, to date, several natural compounds against STAT3 signaling are explored in preclinical trial or clinical trial in ovarian cancer." (PMID 31949487, 2020). "Human ovarian cancer-derived CDEXs containing miR-222 have been shown to induce STAT-3 (signal transducer and activator of transcription 3) mediated M2 polarization ex vivo." (PMID 32793238, 2020). "We also prove for the first time that p-STAT3/NF-kB is loop to increase the expression of IL-6 and VEGF, and IL-6 and VEGF create a feedback to p-STAT3/NF-kB loop in ovarian cancer cells." (PMID 32190078, 2020). "Our results suggest that SPTBN1 suppresses the progression of epithelial ovarian cancer via SOCS3-mediated blockade of the JAK/STAT3 signaling pathway." (PMID 32516133, 2020). "In this review, we focus on the role of STAT3 in tumorigenesis in ovarian cancer and discuss the existing inhibitors of STAT3 signaling that can be promisingly developed as the strategies for ovarian cancer therapy." (PMID 31949487, 2020). "Treatment of ovarian cancer cells with sunitinib or dasatinib alone blocked phosphorylation/activation of STAT3 and SRC, respectively, but it had little effect on other signaling pathways." (PMID 32927828, 2020). "Stat3 is persistently activated in ovarian cancer cells, with a crucial role in tumour onset and progression." (PMID 31778258, 2020).
ovarian carcinoma (continued). "The main action to decrease the growth of ovarian cancer cells was the inactivation of STAT3 and the overexpression of death receptors DR3, DR4 and DR6." (PMID 33142794, 2020). "In ovarian cancer, IL-6 induces STAT3 expression that in turn activates hypoxia inducible factor (HIF), resulting in the resistance of patients with ovarian cancer to chemotherapy with sunitinib." (PMID 32545648, 2020). "We next confirmed that 20 nM rHE4 treatment promoted activation of STAT3 in the ovarian cancer cell line SKOV3, human umbilical vein endothelial cells (HUVECs), and PBMCs." (PMID 32444701, 2020). "On the contrary, resveratrol neutralizes the effect of IL-6 on ovarian cancer cells and reduces level of STAT3 expression." (PMID 31949487, 2020). "STAT3, constitutive expression in ovarian cancer, is correlated with tumor growth and is considered as the upstream gene of NF-kB." (PMID 32190078, 2020). "At last, using RNA interference (RNAi) technology is another approach to block STAT3 signaling and such strategy has also been adopted in ovarian cancer cells." (PMID 31949487, 2020). "Several survival pathways are persistently activated in ovarian cancer cells, including STAT3, SRC, AKT, and MAPK signaling." (PMID 32927828, 2020). "At-EE did not influence vascular endothelial cells directly, but decreased IL-6 and VEGF secreted by ovarian cancer cells to inhibit angiogenesis through inhibition of p-STAT3 and NF-kB activation." (PMID 32190078, 2020). "Relevant to the scope of this review, several studies have demonstrated beneficial effects of combined CD44 and STAT3 signaling downregulation across different cancer models, including ovarian cancer." (PMID 33335857, 2020). "For example, treating ovarian cancer cells with curcumin suppresses activation of STAT3, resulting in decreased cell viability." (PMID 31949487, 2020). "In this study, curcumin reduces fascin expression through JAK/STAT3 pathway inhibition, which interferes with the cellular interactions essential for the metastasis and recurrence of ovarian cancer cells." (PMID 33213437, 2020). "Conversely, inhibition of STAT3 activation results in the dramatic suppression of tumor growth, suggesting that STAT3 signaling is a promising target for ovarian cancer therapy." (PMID 31949487, 2020). "Abnormally activated STAT3 has frequently been found in ovarian cancer cells and clinical specimens." (PMID 31949487, 2020). "STAT3 transcriptional activity has been demonstrated to drive the migration and invasiveness of ovarian cancer." (PMID 33335857, 2020). "Twist basic helix loop helix transcription factor 1 (Twist1), a regulator of EMT, is upregulated in cisplatin-resistant ovarian cancer cells via STAT3 activation." (PMID 32872659, 2020). "Treating cisplatin-resistant ovarian cancer cells with HO-4200 and H-4318 decreases the level of STAT3 target proteins: c-myc, Bcl-2, Bcl-xl, survivin and cyclin D1/D2, giving rise to inhibition of cell survival and induction of apoptosis." (PMID 31949487, 2020). "IL-6 leads to activation of the STAT3 pathway, which is required for ovarian cancer cell migration, motility, survival and proliferation." (PMID 32456078, 2020). "The embryonic stem cell marker Nanog interacts with the cancer stem cell marker CD44 to activate the STAT3 pathway in ovarian cancer cells." (PMID 33023532, 2020). "In all, given the vital role of STAT3 in progress of ovarian cancer and the published reports on STAT3 inhibitors, it is our belief that strategy targeting STAT3 signaling will achieve a great success in clinic of ovarian cancer." (PMID 31949487, 2020). "Apart from the STAT3 pathway, curcumin also inhibits characteristics of ovarian cancer via blocking the other signaling, including sarco/endoplasmic reticulum calcium ATPase, PI3K/Akt and nuclear factor-kappaB pathway." (PMID 31949487, 2020).
ovarian carcinoma (continued). "Activation of STAT3, the upstream gene of NF-kB, is demonstrated to take part in promoting proliferation, drug resistance, and metastasis in ovarian cancer." (PMID 32190078, 2020). "CD97 is a member of the epidermal growth factor (EGF)-seven transmembrane family that signals through Janus-activated kinase 2(JAK2), a signal transducer and activator of transcription 3 (STAT3), to induce paclitaxel resistance in ovarian carcinoma." (PMID 32850313, 2020). "It is reported that constitutively activated STAT3 is involved in EMT of ovarian cancer, as evidenced by the upregulation of Vimentin in STAT3-active cells." (PMID 31949487, 2020). "Huang and co-workers have identified that LC28 significantly inhibits growth of cisplatin-resistant ovarian cancer cells by blocking interaction between STAT3 and DNA140." (PMID 31949487, 2020). "We therefore assessed the sensitivity of 3D spheroid ovarian cancer cells to the inhibition of AKT or JAK2/STAT3 signaling." (PMID 30755611, 2019). "To elucidate the potential mechanism of how STAT3 activation inhibited autophagy in ovarian cancer cells, we detected major members in MAPK and PI3K/AKT/mTOR signal networks by western blot." (PMID 31597912, 2019). "Our results showed that HE4 knockdown dampened the activation of JAK/STAT3 pathway in ovarian cancer in vitro and in vivo." (PMID 31477564, 2019). "Expression of phosphorylated STAT3 coupled with Ki-67 expression, was found to be increased in primary human ovarian carcinoma, particularly in patients with high nuclear expression of pY-STAT3 exhibited poor prognosis." (PMID 31861720, 2019). "For instance, the STAT3-miRNA-92-Wnt signaling pathway regulates spheroid formation and malignant progression in ovarian cancer." (PMID 31815639, 2019). "Recent research has shown that glutamine deprivation results in a decrease in STAT3 phosphorylation at serine 727, which enhances mitochondrial respiration and STAT3 tyrosine phosphorylation in malignant ovarian cancer cells." (PMID 31027222, 2019). "Another study has confirmed that medicinal, mushroom-derived EP exhibited promising antitumor activity through β-catenin and STAT3 pathways in ovarian cancer cells." (PMID 30781890, 2019). "We used multi-omic genome-wide profiling to identify multi-level (Bru-Seq, RNA-Seq, and MS Proteomic) expression signatures of STAT3 KO ovarian cancer cells." (PMID 31534498, 2019). "In paclitaxel-resistant ovarian cancer cells, blocking of STAT3 activity suppresses STAT3 downstream antiapoptotic regulatory genes BCL2L1, MCL1, and BIRC5, which increases paclitaxel sensitivity in paclitaxel-resistant ovarian cancer cells in vitro." (PMID 31861720, 2019). "To investigate the function of STAT3 in human ovarian cancer, we first detected the expression level of STAT3 and pSTAT3 Y705 and S727 in four human ovarian cancer cell lines." (PMID 31597912, 2019). "According to literatures, the presence of constitutively activated STAT3 was found in ovarian cancer tissues and was reported to participate in a variety of cellular processes in ovarian cancer cells including proliferation, invasion, and metastasis." (PMID 31597912, 2019). "We also provide a rationale for mechanism-based therapy involving dual inhibition of STAT3 and AKT signaling in ovarian cancer with PIK3R1 loss or low p85α level." (PMID 30755611, 2019). "Taken together, our data suggests that deletion of STAT3 suppresses cell cycle progression in ovarian cancer." (PMID 31534498, 2019). "The anticancer analogs from curcumin, diarylidenyl piperidone (DAP) derivatives such as HO-3867, HO-4200, HO-4318, inhibit STAT3 activity and sensitize drug-resistant ovarian carcinoma and clear cell carcinoma cells to paclitaxel or cisplatin." (PMID 31861720, 2019). "Further, it was found that hypoxia triggered ovarian cancer cells to secrete more exosomes, which in turn ameliorated dsDNA damage in cisplatin-treated cells and promote cell survival by activating the STAT3 pathway." (PMID 30927928, 2019).